U3 (Small nucleolar RNA U3 )
Synonyms: LOC124906379
Gene: Small nucleolar RNA gene on chromosome 3 (60,856,389 to 60,856,605, reverse strand). Ensembl gene ENSG00000212211.
Gene Ontology:
Biological process: RNA processing
Cellular component: nucleolus
Homologues: Orthologues: chimpanzee U3 (99% identical), macaque U3 (94% identical). Paralogues in human: U3 (80% identical), SNORD3P1 (79% identical), U3 (77% identical), SNORD3G (77% identical), U3 (76% identical), SNORD3E (75% identical), SNORD3H (74% identical), U3 (73% identical), U3 (72% identical), SNORD3D (71% identical), U3 (71% identical), U3 (70% identical), and 11 more.